TNF (tumor necrosis factor)
Diseases named in the same sentence as TNF in open-access papers (continued):
Sharing a sentence is not in itself a finding about the gene and the disease.
periodontitis (continued). "Of note, bone resorption, a hallmark of periodontitis, is mainly affected through RANKL, a vital osteoclast differentiation factor and Tumor Necrosis Factor (TNF)-a, majorly activated by MAPK and NF-κB pathways, indicating a key role of these pathways in osteoimmunology." (PMID 33777111, 2021). "Periodontitis increased mRNA expression of TNF-α and IL-1β in the kidneys." (PMID 34445604, 2021). "Since RA and periodontitis show similarities in high levels of TNF, the periodontal status of RA patients may improve with the use of anti-TNF therapy." (PMID 33193432, 2020). "Increased secretion of pro-inflammatory cytokines, including IL-1, IL-8, IL-6, and TNF-α, during periodontitis development, could exert its effect activating inflammatory pathways in patients with diabetes." (PMID 32431669, 2020). "BMSCs inhibit inflammatory cytokines, including IL-1 and TNF-α, which indicates that the use of BMSCs for the treatment of chronic periodontitis might be feasible." (PMID 32724318, 2020). "Furthermore, TNF-α, together with IL-6, plays a crucial role in establishing the inflammatory state in periodontitis; therefore, they can be considered specific markers of the disease." (PMID 33096800, 2020). "Notably, most of activators of this pathway such as bacterial lipopolysaccharides, prostaglandin E2, IL-1β and TNF-α are abundantly present and active in the process of periodontitis." (PMID 32426538, 2020). "In addition to the contribution to innate immune response, TNF-α also serves as a significant route for alveolar bone resorption in periodontitis for inducing the differentiation and activation of osteoclasts." (PMID 32328131, 2020). "However, the inflammatory mediators the most involved in periodontitis, IL-1β, IL-6, and TNFα were measured, even partially measured, only in 4 studies." (PMID 32698391, 2020). "Furthermore RA patients are prone to develop periodontitis, possibly due to an increase of circulating TNF levels and/or deteriorated motor skills needed for oral hygiene maintenance as a result of damage in the joints." (PMID 33193432, 2020). "In rats: a ligature-induced (Lig) periodontitis model and Aβ25-35-induced model of Alzheimer’s disease (AD) were established; tumor necrosis factor-α (TNF-α), interleukin 1 (IL-1), interleukin 6 (IL-6), and C-reactive protein levels in the hippocampus and cerebral cortex were detected." (PMID 32614834, 2020). "Decreases in IL-1β and TNF-α levels were found to reduce periodontitis progression." (PMID 33343358, 2020). "Since it is well-documented that stimuli like LPS and TNFα can activate the p38 and MEK/ERK pathways in neutrophils and high levels of TNFα are present in periodontitis active sites, we tested the effect of F. alocis pre-treatment on TNFα-induced MAPK signaling cascade." (PMID 32373107, 2020). "Concentrations of TNF-α in the hippocampus and cerebral cortex of rats with AD and periodontitis." (PMID 32614834, 2020). "Since IL-1β and TNF-α are two of the most important inflammatory factors in the progress of periodontitis, we characterized the effects of different dynamic cyclic stress on these protein expressions in LPS-induced inflammatory hPDLCs to extend our observations at the mRNA level." (PMID 31907038, 2020). "In addition, the polymorphisms in NLRP3, IL1R, TNF, IL6, IL2, IL4 and IL4RA genes were associated with periodontitis in the males." (PMID 31978095, 2020). "Since periodontitis is manifested as breakdown of alveolar bone, treatment with anti-TNF might have similar positive effects for the periodontium as for the inflamed joints of RA patients." (PMID 33193432, 2020). "TNFα is a primary inflammatory cytokine that is elevated in active and progressive periodontitis." (PMID 32867386, 2020). "Therefore, CatB plays a critical role in regulating innate immune responses in periodontitis by controlling production of IL-1β and TNF-α." (PMID 32328131, 2020).
periodontitis (continued). "Translating these data into clinic, it is well known that TNF-α, IL-1β and IFN-γ are abundant in periodontitis-associated lesions and are involved in the destructive immune response and in pathogenic alveolar bone remodeling during periodontitis." (PMID 33339125, 2020). "Moreover, no studies have been carried out with healthy individuals with periodontitis on anti-TNF therapy." (PMID 33193432, 2020). "In addition, osteoclasts, also function as antigen presenting cells (APCs) and induced TNF-α production in T cells and helper T cells to moderate inflammation in periodontitis lesion." (PMID 32411181, 2020). "It is well known that TNF-α is expressed during periodontitis." (PMID 32708317, 2020). "It follows that low expression of M1 and M2 in PD patients would be the consequence of local and systemic pro-inflammatory loop lead by IL-6, IL1b and TNFα that down-regulate the macrophage polarization response, reflecting a perturbation in tissue repair in periodontitis." (PMID 32560235, 2020). "Hyperglycemia and a high concentration of TNF-α are two common pathological conditions in diabetic periodontitis patients, but how they affect PDLSCs is still unknown." (PMID 32089705, 2020). "In short, the levels of these cytokines in patients with periodontal disease were significantly higher than in healthy controls; however, other investigators have shown that gingival crevicular fluid levels of TNF-α and IL-8 in periodontitis patients were similar to non-periodontitis patients." (PMID 31382656, 2019). "Similarly, Jagannathan detected extensive macrophage infiltration in the gingival crevicular fluid of patients and animals with periodontitis and investigated several proinflammatory factors and bone resorption factors, such as IL-1β and TNF-α." (PMID 31485288, 2019). "NSAID and tumor necrosis factor inhibitors therapy have been used to treat periodontitis and gingivitis, and thus might decrease gingival or periodontal indices in this study." (PMID 31842923, 2019). "TNF was shown to participate in the pathogenesis of periodontitis." (PMID 31685798, 2019). "The present study aimed to compare variations in quantified tumor necrosis factor-alpha (TNF-α) levels in patients with periodontitis stage 2 grade B (POD2B) and/or type 2 diabetes (T2D) and to identify any relationships between this cytokine and these diseases." (PMID 31355282, 2019). "IL-36γ could perpetuate gingival inflammation by increasing pivotal inflammatory cytokines in periodontitis (IL-1β, IL-6 and TNF-α) and alveolar bone resorption through an increase of the RANKL/OPG ratio in OECs." (PMID 31848404, 2019). "The hypothesis is that adipocytokine molecules are involved in the pathogenesis of inflammatory diseases; if true, individuals who are obese with periodontitis would present increased levels of visfatin, IL-6, and TNF-α in their GCF." (PMID 31365708, 2019). "Despite the absence of exacerbated ABL or osteoclastogenesis by overweight, the condition reduced periodontal macrophage number and partially suppressed pro- (i.e., TNF-α and IL-6) and anti-inflammatory cytokines (IL-10) in periodontium and circulation in periodontitis mice." (PMID 30719451, 2019). "It has been shown that the TNF-α gene SNPs were risk factors for periodontitis in both Caucasians and non-Caucasians populations." (PMID 30755190, 2019). "Mean salivary levels of IL-6 and TNF-α were significantly higher (p = 0.001) in subjects with periodontitis than in healthy subjects: 25.1 (±11.2) vs. 16.3 (±5.0) pg/mL and 29.7 (±17.2) vs. 16.2 (±7.6) pg/mL, approximately 1.5 times and 1.8 times more, respectively." (PMID 29740515, 2018). "Besides osteoclastogenesis, increased apoptosis of osteoblasts induced by IFNγ and TNFα has been demonstrated in mouse models of periodontitis." (PMID 30158833, 2018).
periodontitis (continued). "Thus, the objective of this study is to explore the relationship between IL-6, TNF-α, and visfatin levels and simvastatin treatment through analyzing the GCFs of patients afflicted with chronic periodontitis and type 2 diabetes." (PMID 30186882, 2018). "In our murine model of periodontitis, the TdEno group expressed increased levels of TNFα in the gingival tissues compared with the sham group, suggesting the contribution of anti-mEno1 antibodies to TNFα expression." (PMID 30001173, 2018). "Manifesting high levels of cytokines, such as IL-1β, IL-6, and TNF-α, periodontitis has an immunologic profile similar to that of RA and both diseases are associated with elevated concentrations of matrix metalloproteinases (MMPs) and low concentrations of tissue inhibitors of MMP (TIMPs)." (PMID 30211216, 2018). "Experimental models demonstrate that the development of periodontitis in diabetic rats involves a high expression of proinflammatory cytokines (TNF-α, IL-1β, IL-6) and destructive tissue factors as advanced glycation end products (AGEs) without significant changes in commensal oral microbiota." (PMID 30356347, 2018). "Gene expression profiling in circulating monocytes in this experimental model showed that periodontitis induced a M1-like specific signature with high levels of TNF-α and IL-6 as compared to controls, indicating that a M1-like phenotype of macrophages is induced by periodontitis." (PMID 29507865, 2018). "Also, when compared to healthy patients, subjects with gingivitis or periodontitis produce high levels of inflammatory mediators, such as IL-6 and TNF-α." (PMID 29740515, 2018). "IL-6, CXCL-8, and TNF-α may have an important role in the pathogenesis of chronic periodontitis and detection of these cytokines may be beneficial to identify periodontitis patients." (PMID 29670909, 2018). "It is known that hypoxic exposure increases alveolar bone loss in rats both with and without experimental periodontitis, as well as the level of some important inflammatory mediators during periodontitis pathogenesis, such as NO and tumor necrosis factor α." (PMID 30622434, 2018). "Women with periodontitis exhibited significantly higher levels (p = 0.001) of salivary IL-6 and TNF-α compared with the healthy group: 25.1 (±11.2) pg/mL vs. 16.3 (±5.0) pg/mL and 29.7 (±17.2) pg/mL vs. 16.2 (±7.6) pg/mL, approximately 1.5 and 1.8 times more, respectively." (PMID 29740515, 2018). "In particular, tumor necrosis factor-α (TNFα) and interferon-gamma (IFNγ) are believed to promote bone degradation in periodontal disease, because periodontal tissues in patients with periodontitis are infiltrated by CD4+ and CD8+ T cells, which produce these cytokines." (PMID 30158833, 2018). "Likewise, other studies have demonstrated that the presence of periodontitis is a poor prognostic factor in RA patients treated with anti-TNFα agents." (PMID 29387048, 2017). "IL‐1β and TNF‐α are proinflammatory cytokines that are involved in the initiation and progression of chronic inflammation, and they are critical mediators in the progression of periodontitis." (PMID 29744190, 2017). "Therefore, we readily understand the high proportions of IL-1β and TNF-α and a more aggressive immune reaction in peri-implantitis compared with periodontitis." (PMID 28864780, 2017). "The effects of B and T cells on bone are mediated by several key cytokine regulators of bone metabolism, including the inflammatory cytokines tumor necrosis factor-α (TNF-α) and interferon-γ, which have been implicated in bone loss in RA, periodontitis, postmenopausal osteoporosis, and HIV." (PMID 29312334, 2017). "As for RA, disease progression seen in chronic periodontitis consists of the continuing presence of high levels of pro-inflammatory cytokines including IL-1β and TNF-α and low levels of anti-inflammatory cytokines like IL-10 and transforming growth factor-beta (TGF-β)." (PMID 28061876, 2017).
periodontitis (continued). "Tumor necrosis factor (TNF)-α is a pro-inflammatory cytokine expressed in periodontitis." (PMID 29240821, 2017). "Comparison of mean TNF-α level between periodontitis and control groups before and after the treatment showed significant differences (P< 0.05); Although, salivary IL-1α concentration increased after the treatment, the change was not statistically significant (p=0.056)." (PMID 29238418, 2017). "In a subset of patients with severe periodontitis, locally produced proinflammatory mediators—such as IL-1β, IL-6, and TNF-α—can enter systemic circulation and induce an acute-phase response in the liver that is characterized by an increased level of C-reactive protein (CRP)." (PMID 28243243, 2017). "Increased levels of IL-6 have been detected in the crevicular fluid of active sites compared with healthy sites of patients with refractory periodontitis and exposure to lipopolysaccharide from the P. gingivalis induces elevated levels of IL-6 and TNF-α in primary gingival mouse cell lines." (PMID 28632755, 2017). "Gingival tissues of chronic periodontitis patients exhibit significantly higher levels of pro-inflammatory cytokines IL-1β, IL-6, IL-8, and TNFα than those of periodontally healthy subjects, hence it is possible that periodontal pathogen OMVs are contributing to this response." (PMID 28890719, 2017). "However, in T2DM subjects, the concentration of TNF-α was significantly lower in the severe periodontitis group compared with the moderate periodontitis group (P = 0.042)." (PMID 29109737, 2017). "Therefore, the attenuation of sclerostin-positive osteocytes in IFX treated rats implicates the stimulatory effect of TNF-α on osteocytic sclerostin expression in type 1 diabetes with periodontitis." (PMID 29240821, 2017). "AD patients with periodontitis have higher levels of serum IL-6 and TNF-α than uninfected controls." (PMID 28284226, 2017). "Based on significant correlations between serum PGE2 level and probing depth, clinical attachment loss (CAL), and GCF TNF-α in PTB, periodontitis may increase the risk of labor triggers and hence contribute to preterm labor onset." (PMID 28243243, 2017). "Type 1 diabetes with periodontitis shows elevated TNF-α expression." (PMID 29240821, 2017). "The result showed that IL-1β and TNF-α were upregulated in LPS-induced periodontitis rats." (PMID 27216891, 2016). "Finally, cluster 9 genes (n = 8) were similar to expression patterns for cluster 8, except for positive correlations with TNFα in periodontitis." (PMID 27486459, 2016). "Inactivation of those substrates by dephosphorylation lead to the negative regulation of signaling pathways involved in inflammatory responses induced by the proinflammatory cytokines like TNF-α, which is also increased in serum and gingival cervical fluid of patients with periodontitis." (PMID 27995146, 2016). "Thus, the rats in which the levels of TNFα mRNA were increased in the ligature-induced periodontitis compared with the control were analysed." (PMID 27716163, 2016). "TNF-α may potentiate periodontitis by stimulating the release of eicosanoids, as well as other cytokines such as IL-1." (PMID 27110759, 2016). "Cytokines like IL-1α, IL-1β, IL-6, IL-8, and TNF-α have been documented to be involved in immune activation, increased cytotoxic activity, and cytokine-mediated osteoclastic bone resorption in aggressive forms of periodontitis." (PMID 27642305, 2016). "Thus, the data of rats (n = 16) in which the levels of TNFα mRNA were increased more than 1.4-fold in the ligature-induced periodontitis compared with the control were analysed." (PMID 27716163, 2016). "TNF-α is also known for its substantial role in periodontitis." (PMID 26171113, 2015). "Circulating TNF-α and IL-6 are also thought to become elevated as a result of intrauterine infections in humans, however our results showed that only IL-6 was significantly increased in mice with induced periodontitis." (PMID 25806806, 2015).
periodontitis (continued). "The pivotal role of these cytokines in periodontitis is supported by reports that attachment loss is reduced in periodontitis patients with RA after anti-TNF treatment, and that local gingival administration of recombinant TNF-α or IL-1β exacerbates experimental periodontitis in rats." (PMID 26241961, 2015). "In addition, these authors found amongst subjects with periodontitis,obese or normal weighing, a significant increase in TNF-α levels in sites with probing depths greater than 5mm." (PMID 26330934, 2015). "Thus, the objective of this study was to assess the serum levels of adiponectin, leptin and TNF-α of periodontally healthy (PH) normal weight (NW) subjects, NW subjects with chronic periodontitis (CP), PH obese subjects and obese subjects with CP." (PMID 26330934, 2015). "The hallmarks of periodontitis are host inflammatory events, including the release and activation of inflammatory mediators and cytokines such as interleukins (ILs) and tumor necrosis factor α (TNF-α), as well as proteolytic enzymes such as matrix metalloproteinases (MMPs)." (PMID 26686060, 2015). "Furthermore, subcutaneous administration of recombinant human TNF-α accelerates the progression of experimental periodontitis." (PMID 25657893, 2015). "This is, to the best of our knowledge, the first case of periodontitis-associated RA healing, through periodontal treatment only, without the use of DMARDs and/or TNF inhibitors." (PMID 25501069, 2014). "In patients with moderate chronic periodontitis, the immunological homeostasis in relation to neutrophil turnover seems to be sustained, maybe because of IL-1β, which compensates for TNF-α, resulting in limited inflammation." (PMID 25299619, 2014). "In addition, a previous study did not identify a statistically significant difference in the total amount of TNF-α prior to and following periodontal treatment in chronic periodontitis subjects." (PMID 24944641, 2014). "A possible explanation could be the turnover of neutrophils in gingival tissue, which seems to be reduced in patients with aggressive periodontitis because of less TNF-α." (PMID 25299619, 2014). "TNF-α is considered to be a major cytokine involved in the pathogenesis of periodontal disease, affecting the consequences of the tissue destruction and the erosive reaction in periodontitis." (PMID 24137277, 2013). "Elevation of IL-1 and TNF-α levels induced by periodontitis may play a crucial role in the development of a variety of systemic diseases." (PMID 23951003, 2013). "The results suggest that ILs and TNF-α may be expressed through different pathways in the pathophysiology of periodontitis." (PMID 24137277, 2013). "Elevated CRP & TNF-α level in periodontitis patients have been reported by several groups." (PMID 24198887, 2013). "Therefore, in the current study, the levels of IL-6, IL-8 and TNF-α expressed in the human gingival tissues of patients with periodontitis were investigated." (PMID 24137277, 2013). "It has been suggested that the protein expression levels of IL-6, IL-8 and TNF-α may be clinical parameters of gingival and periodontal inflammatory conditions." (PMID 24137277, 2013). "Conceptually, this makes p38 inhibitor strategies appealing as a host-modulating agent for treatment of periodontitis because physiologic bone turnover (induced by PTH/PTHrP) would occur, but inflammatory bone loss (induced by LPS, IL-1β, and TNF-α) would be pharmacologically antagonized." (PMID 22315682, 2012). "Some studies reported by these authors establish that patients suffering from severe Periodontitis have an increased local production of inflammatory cytokines (IL-1B, TNF-α and IL-6) and a moderate systemic inflammatory response characterized by raised concentrations of CRP, and other mediators." (PMID 28348657, 2011).